HMGA2 (high mobility group AT-hook 2)
Diseases named in the same sentence as HMGA2 in open-access papers (continued):
Sharing a sentence is not in itself a finding about the gene and the disease.
tumor (continued). "Specifically, tumours with high levels of HMGA2 protein expression formed VM channels, whereas tumours with low HMGA2 expression did not present the same effect." (PMID 28533522, 2017). "In agreement with the well‐known function of HMGA2 in promoting self‐renewal of stem cells and GB tumor initiation capability, Dov attenuated GB sphere formation and increased apoptosis in sphere‐forming GB cells." (PMID 28500786, 2017). "Meanwhile, we validated that the expression levels of HMGA2 (or PTEN) were increased (or decreased) in the tumor tissues from mice." (PMID 28522832, 2017). "Consistent with the known function of LIN28 and HMGA2 in GB self‐renewal, Dov reduced GB tumor sphere formation." (PMID 28500786, 2017). "In order to find possible molecular targets of DNase I among tumour-specific genes, analysis of Hmga2, Fos, Myc, Nras and Jun genes known to be carcinogenesis markers was performed." (PMID 28222152, 2017). "The tumor-suppressive role of the let-7 miRNA family is antagonized by the self-promoting oncogenic triangle composed of the transcription factor HMGA2, the Insulin-like growth factor-2 mRNA-binding proteins (IGF2BP1) and LIN28B." (PMID 29383160, 2017). "Inhibition of Lin28 promotes Let-7 expression leading to inhibition of HMGA2 which is a driver of tumor metastasis." (PMID 28400788, 2017). "Involved in the control of fetal development, HMGA2 also has a central role in tumor growth and metastasis." (PMID 28542306, 2017). "Consistent with our results, increased Twist1 and VE-cadherin expression levels were observed in tumours with high HMGA2 expression, while the converse relationship was observed in tumours with shRNA-mediated silencing of HMGA2." (PMID 28533522, 2017). "Western blot analysis of E-cadherin, vimentin, and HMGA2 expression confirmed the tumor aggressiveness of CL1-5 cells." (PMID 29079814, 2017). "We also found that the overall survival rate was much lower in patients with tumours positive for HMGA2 and VM." (PMID 28533522, 2017). "For DNase I treatment, a 1.5–2-fold decrease in the abundance of tumour-specific fragments of Myc, Hmga2 and Jun was observed, in the case of Hmga2 to the level of healthy mice, while the abundance of Fos was slightly increased." (PMID 28222152, 2017). "It was previously shown that Lin28 located upstream of HMGA2 can upregulate HMGA2 and that HMGA2 promotes GB stem cell renewal and tumor initiation in GB cells." (PMID 28500786, 2017). "The major differences were observed for the following types of sequence: GC-poor sequences, tandem repeats (sequences with high stability) and fragments relevant to tumour-specific genes (Hmga2, Fos, Myc and Jun)." (PMID 28222152, 2017). "HMGA2 has emerged as a tumour biomarker due to its tumour-specific overexpression in many human cancers." (PMID 28533522, 2017). "Taken together, our data suggest that HMGA2 directly targets Twist1 and promotes the expression of Twist1 and VE-cadherin, resulting in the formation of VM and enhanced tumour invasion and metastasis." (PMID 28533522, 2017). "One CDK4 amplified tumor with grey-zone MDM2 amplification showed only a low HMGA2 copy number increase." (PMID 27662657, 2016). "Histological and immunofluorescent analyses showed restored cellularity and tumor neo-angiogenesis in FOXM1b- or PLAU-expressing GICs that were devoid of HMGA2." (PMID 27259253, 2016). "In the 2013 edition of “WHO classification of tumours of soft tissue and bone”, the only genetic information on these tumors is that expression of full-length HMGA2 was detected by RT-PCR in myolipoma of the pelvic cavity." (PMID 26857357, 2016). "The EGCG-induced up-regulation of let-7b led to down-regulation of high mobility group A2 (HMGA2), a target gene related to tumor progression." (PMID 26754091, 2016). "The protein levels of HMGA2 were determined by immunohistochemistry in 156 tumour samples and the protein expression was correlated with gene expression." (PMID 26858029, 2016).
tumor (continued). "Carcinomas ex PA have been reported to generally retain HMGA2 rearrangements along with further gene alterations in tumor progression making HMGA2 a potential marker for SDCs arising in PA." (PMID 27662657, 2016). "HMGA2 protein regulates the transcription of several EMT-related genes and thus is closely associated with tumor invasion and metastasis." (PMID 26893968, 2016). "In previous studies, HMGA2 was identified as the target gene of several microRNAs, such as Let-7, which is considered to be a tumor suppressor gene in multiple types of cancer." (PMID 26818837, 2016). "The analysis results revealed that the patients with tumors exhibiting low expression of HMGA2 have less possibility of lymph node metastasis, well prognosis of clinical and tumor stage." (PMID 26818837, 2016). "In tumours with apparent co-regulation of expression of HMGA2 and MYCN, there was a significantly better outcome when both genes were downregulated compared to the alternatives (log rank test, p = 0.040)." (PMID 26858029, 2016). "Successful transfection of cells with fluorescent siRNA as well as knockdown of the oncogene HMGA2 in tumor cells with specific siRNAs were demonstrated elsewhere." (PMID 28773519, 2016). "In total, 86 (55 %) of the tumour samples were scored with a high expression level of the HMGA2 protein." (PMID 26858029, 2016). "Let-7b has several target genes related to tumor progression including HMGA2 (high mobility group A2)." (PMID 26754091, 2016). "Taken together, data proposed the suppressive role of miR-204 on tumor and the consequences of its inactivation on the oncogenic activity of HMGA2." (PMID 27095441, 2016). "Compared to tumours with low HMGA2 mRNA expression, mean expression of let-7a, let-7c, let-7d and let-7f was significantly lower in tumours with high expression of HMGA2 whereas let-7d was higher." (PMID 26858029, 2016). "Other study showed that low expression of let-7 is related to tumor invasiveness and prognosis by targeting HMGA2." (PMID 27322246, 2016). "When focusing on the tumours with seemingly co-regulated HMGA2 and MYCN expression, we found a significantly better outcome when both genes were downregulated compared to the remainders." (PMID 26858029, 2016). "Here, we investigated an epigenetic and possibly direct role for HMGA2 in the modulation of E-cadherin, a major suppressor of tumour invasiveness." (PMID 25492890, 2015). "ESFT tumour cell growth reduction resulting from over-expression of let-7a was shown to be mediated through HMGA2 repression, a target of let-7a along with IGF2BP1 and Lin28." (PMID 26204834, 2015). "The tumor expressed HMGA2 and HMGA1 even though 12q14-15 and 6p looked normal by G-banding analysis." (PMID 25621995, 2015). "Remarkably, in 93% of the patients analyzed the HMGA2 mRNA presence in peripheral blood correlated with the protein expression in the tumor tissue." (PMID 25749380, 2015). "Our data together with recent reports of increased HMGA2 expression in AT/RT suggest a broad reliance on the LIN28/HMGA2 pathway in this tumor." (PMID 25638158, 2015). "Lastly, to evaluate the role of Hmga2 in intestinal tumorigenesis in the context of Let-7 depletion we examined tumor burden in Vil-Lin28bMed and Vil-Lin28bMed/Hmga2+/IEC-KO mice." (PMID 26244988, 2015). "In this vein, let-7 over-expression or HMGA2 knock-down both led to suppression of in vitro growth of G401 rhabdoid tumor cells, although the authors admit that HMGA2 is only one potential target of let 7a/7b and the study was focused on this axis only." (PMID 26204834, 2015). "HMGA2, Twist1 and ZEB1 expressions were significantly higher in samples with poor prognosis with stage IV tumor expressing highest levels of HMGA2, Twist1 and ZEB1." (PMID 25868853, 2015). "This phenomenon consists with the results in a previous report that in tumour cells, Wnt2 was one of the genes with over 2-fold down-regulation by HMGA2." (PMID 25300915, 2015).
tumor (continued). "As an oncoprotein, HMGA2 is overexpressed in many tumours and plays important roles in stem cell self-renewal, proliferation and differentiation." (PMID 25300915, 2015). "RT-PCR with the primer sets HMGA2–846F1/HMGA2–1021R and HMGA2–846F1/HMGA2–1112R amplified cDNA fragments from the tumor (lanes 5–6)." (PMID 25621995, 2015). "Subsequently, we assessed the expression of the HMGA2 protein, by immunohistochemistry, in the tumor sections and their normal counterparts obtained from the same patients enrolled for blood sampling." (PMID 25749380, 2015). "Molecular analysis of the first tumor showed that both transcript 1 (NM_003483) and transcript 2 (NM_003484) of HMGA2 were expressed." (PMID 26043835, 2015). "HMGA2 immunostainings showed higher intensities within the invasive front of the tumours than in the centre of the tumour in both species." (PMID 25245141, 2014). "Significant correlation between HMGA2 overexpression and tumor cell invasion has been detected in breast cancer and gastric cancer." (PMID 25548562, 2014). "In turn, Let-7 miRNAs have been reported to play role as tumor suppressor, mainly by repression of oncogenes and key regulators of various mitogenic pathways, such as Myc, Hmga2, Ras, JAK and STAT3." (PMID 24498170, 2014). "The respective p-values of the tumour and cell line sample groups were p = 0.000 despite of the cell line sample group within the HMGA2/GUSB real time PCR showing a p-value of 0.001." (PMID 25245141, 2014). "In all sections positive nuclear staining for HMGA2 was detected in the tumour cells that were located in the centre and/or at the invasive front of the tumours as well." (PMID 25245141, 2014). "HMGA2 was up-regulated when HPRT was used as endogenous control gene within the tumour (p = 0.002) and cell line samples (p = 0.024) when compared to the non neoplastic samples." (PMID 25245141, 2014). "The herein reported immunohistochemical staining in human sections showed positive HMGA2 staining within the centre and the invasive front of the tumour sections in only two patients." (PMID 25245141, 2014). "Thereby, with exception of two cases, the percentages of positive nuclei for HMGA2 were higher at the invasive front of the tumour sections than in the centre of the tumours." (PMID 25245141, 2014). "Secondly we examined the biological consequence of reduced let-7 expression in NETs and metastasis by western blot analyses and immunohistochemistry on paired FFPE tumor and metastases tissues for HMGA2, BACH1 and MMP1." (PMID 25546138, 2014). "HMGA2 is found at the invasive front of the tumor to promote tissue invasion and tumor recurrence following therapy." (PMID 24723911, 2014). "Re-expression of HMGA2 is reported to be associated with the formation of malignant and benign tumours, but the exact mechanism of HMGA2 acting in tumour formation and progression is still unclear." (PMID 24914948, 2014). "In a recent study, the HMGA2 protein expression was demonstrated to be significantly higher in tumour tissues compared with adjacent normal tissues." (PMID 24914948, 2014). "In different tumours, the HMGA2 3′UTR was described to be affected by deletions or rearrangements leading to a loss of let-7 complementary target sequences." (PMID 24914948, 2014). "Staining intensities of HMGA2 of tumour cells located at the invasive front were as follows: patient 4 – moderate (2+), patient 5 – strong (3+)." (PMID 25245141, 2014). "In general, an inverse correlation of let-7 and HMGA2 is a frequent finding in many types of human neoplasias." (PMID 25245141, 2014). "HMGA2 was up-regulated when HPRT was used as endogenous control gene within the tumour (p = 0.032) and cell line samples (p = 0.000) when compared to the non neoplastic samples." (PMID 25245141, 2014).
tumor (continued). "In the sections of patients 4 and 5 positive nuclear staining for HMGA2 was detected in the tumour cells that were located in the centre and/or the invasive front of the tumours." (PMID 25245141, 2014). "We show that both WNT10B and HMGA2 are highly expressed in a subset of human primary TNBC tumours correlating with predictive poor survival outcome in both basal-like and TNBC patients." (PMID 23307470, 2013). "In diverse cancers, HMGA2 promotes tumor invasiveness through activation of genes that suppress cell adhesion and promote migration." (PMID 23846349, 2013). "Since our in vitro cultures establish HMGA2 regulation of histone H3K9 and H3K27 acetylation, we next examined the extent to which human PDAC tumor samples that overexpress HMGA2 show evidence of increased histone H3K9 and H3K27 acetylation." (PMID 23696899, 2013). "Similar to LIN28A-transduced GBM neurosphere lines, hNSC-derived tumor cells showed increased expression of HMGA2." (PMID 23846349, 2013). "Treatment of TNBC-derived cell lines and primary tumour mouse cells with known Wnt pathway inhibitors down regulates expression of HMGA2 and cell proliferation markers." (PMID 23307470, 2013). "Collectively, these observations suggest that Runx3 serves as an important tumor suppressor against Ras-induced tumorigenicity by safeguarding against Hmga2-mediated plasticity and stemness." (PMID 23950932, 2013). "We identified HMGA2 to be highly expressed in Wnt10bLacZ TN tumours and in both human TNBC cell lines and primary TNBC tumour samples." (PMID 23307470, 2013). "The strong correlation between HMGA2 expression and tumor invasiveness has prompted further research on this molecule and related pathways." (PMID 23077401, 2012). "This list includes PLA2G4A, HMGA2, TAGLN and TUSC3, all of which have been implicated in other neoplasias." (PMID 23046790, 2012). "HMGA2 is being studied for its oncogenic properties, stem cell self-renewal, DNA damage response, and tumor cell growth and differentiation." (PMID 23077401, 2012). "Given that let-7 simultaneously inhibits multiple oncogenic pathways that are involved in most steps of tumorigenesis (such as RAS, MYC, and HMGA2), restoration of let-7 expression in tumor cells provides a novel therapeutic strategy to treat cancer." (PMID 22970210, 2012). "HMGA2 is the most highly predicted target of the Let-7 family of microRNA (miRNA) in the genome, suggesting reduced Let-7 expression as an alternative explanation for the pattern of HMGA2 expression in C5 tumours." (PMID 21533284, 2011). "Here we have shown that each pathway element is specifically expressed in a way that would account for the profound over-expression of HMGA2 and other oncofetal proteins in a large proportion of C5 tumours." (PMID 21533284, 2011). "Immunohistochemical analysis also demonstrated that C5 tumours consistently express high levels of HMGA2 protein (∼95% at 3+; p = 0.02, two sided Fisher's exact test)." (PMID 21533284, 2011). "Heterogeneous expression of HMGA2 and lin28B was observed in let-7a-treated tumors suggesting non uniform distribution of synthetic miRNA within the tumor." (PMID 21853155, 2011). "Concomitant down regulation of Let-7 and augmented HMGA2 expression results in less differentiated tumours with stem cell-like characteristics." (PMID 21533284, 2011). "For example, the 206-fold up-regulation of the transcriptional regulator and oncogene HMGA2 in one tumor would have been missed if only assayed by microarray." (PMID 20174472, 2010). "Of particular concern in this respect is the significant upregulation in Hmga2 mRNA and protein levels, given the oncogenic role of Hmga2 in many tumours." (PMID 20976144, 2010).
tumor (continued). "In benign tumours of mesenchymal origin, HMGA2 is often rearranged by translocation, and the resulting chimeric transcripts are formed by fusion of the DNA-binding domains, coded by exons 1-3, to ectopic sequences." (PMID 20576167, 2010). "Aberrations in the chromosomal region 12q14-15 that affect HMGA2 are frequent in a variety of tumours." (PMID 20576167, 2010). "Twenty-five of these (46%) showed a high expression (3+ and 2+) of HMGA2, and 15 (27%) tumours showed low expression (1+), and 15 (27%) tumours were negative immunoreactions." (PMID 19156147, 2009). "The altered form of the high-mobility group A2 (HMGA2) gene is somehow related to the generation of human benign and malignant tumours of mesenchymal origin." (PMID 14647145, 2003). "It is concluded that HMGA2 is highly expressed in a very broad range of tumor entities." (PMID 40518465, 2025). "It is to be expected that larger tumor samples may contain focal HMGA2 staining in a fraction of cases." (PMID 40518465, 2025). "Not only do they share HMGA2 rearrangements but in more than one-third of the cases, areas with the typical PA morphology were part of both the monophasic and biphasic neoplasms described in this study (in 32% and 40% of the monophasic and biphasic tumors, respectively)." (PMID 40033554, 2025). "Additionally, HMGA2 promotes tumor progression by regulating macrophage proliferation, migration, polarization and angiogenesis via CXCL12/CXCR4-dependent mechanisms." (PMID 40351420, 2025). "HMGA2 abundance appeared lower in areas of lobular vs. stromal tumor location in KPC tumors." (PMID 41006303, 2025). "In 3 cases with biphasic morphology, HMGA2 was only detected in the abluminal layer of tumor cells." (PMID 40033554, 2025). "HMGA2 was upregulated in LSCC samples and positively correlated with circshkbp1Levels of circSHKBP1, miR-766-5p, and HMGA2 were associated with clinical characteristics of tumor patients, including lymph node metastasis status and TNM staging." (PMID 41267993, 2025). "Reduced let-7 levels lead to increased HMGA2 expression, promoting tumor growth." (PMID 40260417, 2025). "In this study, we present an extensive analysis of the immunohistochemical and molecular-genetic features of the emerging canalicular tumor of the salivary glands, defined by HMGA2 rearrangement and a unique anastomosing canalicular and trabecular arrangement of monophasic or biphasic epithelium." (PMID 40033554, 2025). "In this regard, incorporating analyses of chromosomal deletions (particularly 9p), as well as markers such as CD105 and HMGA2::TMTC2, may enhance understanding of tumor biology and aid in risk stratification." (PMID 41264057, 2025). "Several studies have described morphological features that could characterize HMGA2-altered neoplasms." (PMID 40338436, 2025). "In summary, these findings suggested that patients with high HMGA2 expression levels may have less immune cell infiltration (especially M1 macrophages infiltration) at the tumor site and may be less responsive to immune checkpoint inhibitor therapy." (PMID 40703517, 2025). "To date, numerous studies have shown that HMGA2 expression is dysregulated in different human tumor tissues, and its high expression may be a critical step in the pathogenesis of malignant tumors." (PMID 39591457, 2024). "Importantly, slower growth and smaller tumor sizes were observed in HMGA2-deleted cells than in control vector-treated cells after subcutaneous implantation into SCID mice." (PMID 38493165, 2024). "At the protein level, HMGA2 can serve as a prognostic indicator for cancer patients.Therefore, detecting the expression levels of HMGA2 in tumor tissues can provide clinicians with important prognostic data, but further research is needed to understand how it affects tumor prognosis." (PMID 39591457, 2024). "In this literature review, we highlight the EMT-induced role of HMGA2 in tumor development and invasion and discuss signaling pathways that may be affected by HMGA2." (PMID 38361784, 2024).